INS (insulin)
Diseases named in the same sentence as INS in open-access papers (continued):
Sharing a sentence is not in itself a finding about the gene and the disease.
type 2 diabetes (continued). "Several new loci for type 2 diabetes have been additionally identified through GWAS for quantitative traits related to glucose metabolism, such as fasting plasma glucose (FPG) and 2-hour glucose levels (Meta-Analyses of Glucose and Insulin-related traits Consortium [MAGIC])." (PMID 22046406, 2011). "In the absence of functional insulin signaling as in type 2 diabetes or obesity, an agent such as E4orf1 that up-regulates insulin independent glucose disposal through Ras activation may be valuable." (PMID 21886789, 2011). "A prospective randomized in 130 hospitalized noncritically ill patients with type 2 diabetes showed that basal-bolus insulin regiment (using a daily long-acting insulin analog with preprandial rapid-acting insulin analog) was superior to a standard sliding scale protocol." (PMID 20811546, 2011). "In Type 2 diabetes beta-cells are also dysfunctional and damaged, possibly in response to peripheral insulin resistance, hyperglycemia, hyperlipidemia and cytokines, leading to a relative lack of insulin." (PMID 21935477, 2011). "This has been supported by a plethora of research that has consistently demonstrated that SMBG is a key contributor to good glycaemic control among insulin-using patients with type 1 (T1DM) and type 2 diabetes (T2DM)." (PMID 20482765, 2010). "Patients are eligible for the study if they are between 40 and 80 years old, diagnosed with type 2 diabetes more than one year ago, treated by a general practitioner, not on insulin treatment, and with HbA1c ≤7.5%, systolic blood pressure ≤145 mmHg and total cholesterol ≤5.2 mmol/l." (PMID 20459820, 2010). "They demonstrated that an intensive insulin regimen in type 2 diabetic patients reversed the insulin resistance in muscle and liver as well as increased the beta cell insulin secretion without further use of insulin, claiming, that this would be caused by some "metabolic memory"." (PMID 20836897, 2010). "Self-monitoring of blood glucose (SMBG) which has been found to be effective for patients with type 1 diabetes and type 2 diabetes if they are taking insulin appears not be effective in improving HbA1c in with patients with type 2 diabetes using oral hypoglycaemic drugs." (PMID 21073714, 2010). "Many did not know the benefits of insulin for poorly controlled type 2 diabetes." (PMID 19356239, 2009). "Furthermore, it has been shown that HK2 expression is stimulated by insulin in healthy individuals but not in obese or type 2 diabetes patients." (PMID 19668377, 2009). "The key results from this study were that 1) calpain-10 mRNA levels were elevated in pancreatic islets of patients with type 2 diabetes and 2) there was a positive correlation between calpain-10 expression and insulin release in response to arginine in non-diabetic but not in diabetic donors." (PMID 19688040, 2009). "The aim of this investigation was to provide an initial assessment of insulin sensitivity and secretion indices using a widely available and easily standardized liquid meal tolerance test in subjects with normal fasting glucose (NFG), impaired fasting glucose (IFG) or type 2 diabetes." (PMID 19476649, 2009). "In this study, we compared LM50 with human insulin mix 50 (50% regular human insulin, 50% human insulin isophane suspension; Novolin® 50, Novo Nordisk, Bagsværd, Denmark) for the control of 2-h PPBG excursion following a standard test meal in Chinese patients with type 1 or type 2 diabetes." (PMID 18657196, 2008). "Studies of the effect of hyperglycaemia and hyperinsulinaemia on neutrophil functions and proinflammatory gene expression in Type 2 diabetic patients do not provide insight into the distinct effects of elevated glucose and insulin concentrations, since both are present at the same time." (PMID 18290856, 2008).
type 2 diabetes (continued). "The original finding that GLP-1 infusion increased insulin release and reduced fasting plasma glucose and glucagon in Type 2 diabetic subjects resulted in the development of the first GLP-1 receptor agonists, and the recent licensing of exenatide for the treatment of Type 2 diabetes." (PMID 18959599, 2008). "Having established that UCP-2 is upregulated under conditions present in type-2 diabetes (high glucose concentrations and free fatty acid concentrations) we sought to establish if the endogenous UCP-2 protein expressed in human islets plays a role in insulin secretion." (PMID 18167556, 2008). "No SNP was associated with type 2 diabetes in either African Americans or European Americans, but among nondiabetic European American individuals, ARNT SNPs rs188970 and rs11204735 were associated with acute insulin response (AIRg; p =< 0.005)." (PMID 18366646, 2008). "The selection criteria enabled us to recruit people with less-complicated type 2 diabetes, who may represent a large number of patients, such as those with new diagnoses and not requiring insulin." (PMID 19055828, 2008). "On the other hand, in type 2 diabetes,the insulin functionality gradually weakens, but does not completely stops.Since the diabetic more or less has the endogenous insulin supply, diabetestherapies mostly focus on exercises or regimens consuming or suppressingexcessive glucose in blood." (PMID 18566688, 2008). "In a recent study, the postprandial glucose and insulin responses of type 2 diabetes patients were found not to be affected, and in healthy subjects the postprandial blood glucose levels were not affected, but the insulin levels were reduced when apple cider vinegar was consumed prior to the meal." (PMID 18439313, 2008). "In nonobese people with type 2 diabetes, including those in whom SUs secondarily fail, there are reports of significant restoration of β-cell secretory activity after a brief period of intensive insulin therapy." (PMID 18959471, 2008). "Patients with type 2 diabetes, who do not use insulin, but self monitor blood glucose, have not shown significant reduction in A1c levels in many prospective studies and randomized controlled trials and a small effect of 0.39% decrease in A1c levels compared to control in one systematic review." (PMID 18501012, 2008). "Notably, patients with LADA generally do not respond significantly to OADs and will require insulin therapy at an earlier stage than other patients with type 2 diabetes." (PMID 17448241, 2007). "(These data indicate that CIDE-A expression was more closely correlated to plasma insulin levels and weight than to fasting blood glucose and suggests that increased CIDE-A expression precedes elevated blood glucose during the onset of obesity-induced type 2 diabetes)." (PMID 17472743, 2007). "Whether or not the processes involved in foam cell formation modulate insulin signaling, glucose tolerance, and onset of type 2 diabetes, is currently unknown." (PMID 16787541, 2006). "The first inhaled human insulin (INH, Exubera® (insulinhuman [rDNA origin]) Inhalation Powder) was recently approved by the European Commission and the US Food and Drug Administration to deliver effective glycemic control in adult patients with type 1 or type 2 diabetes." (PMID 16901335, 2006). "Inasmuch as Metabolic Syndrome emphasizes the condition of insulin resistance, the syndrome itself is not type 2 diabetes, but a large percentage of the people with Metabolic Syndrome will develop type 2 diabetes if the condition of insulin sensitivity is not improved." (PMID 16232315, 2005). "As a general rule, SC insulin should not be used in patients with type 2 diabetes requiring surgery and general anesthesia, since insulin absorption from the SC tissue could be quite variable, particularly in obese individuals." (PMID 15916471, 2005).
type 2 diabetes (continued). "Although type 2 diabetes mellitus (T2DM) is not a vitamin D-dependent disease, there is evidence that insulin sensitivity and ß-cell function can be improved in patients with newly diagnosed T2DM by daily vitamin D supplementation of 5000 IU." (PMID 40565034, 2025). "Type 2 diabetes mellitus (T2DM) is defined as the lack of uptake of sugar into the muscles, fat and liver in response to their resistance to insulin." (PMID 41210503, 2025). "Type 2 diabetes mellitus (T2DM) is a metabolic disorder arising from the lack of insulin cell response (insulin resistance), consequently resulting in subsequent hyperglycemia." (PMID 41497809, 2025). "Therefore, insulin therapy may not consistently reflect the underlying disease subtype, limiting its utility in differentiating MODY from type 2 diabetes." (PMID 40966384, 2025). "Because overt type 2 diabetes is rare in this age cohort, we hypothesized that any Mtb-related deleterious cardiometabolic effects might instead manifest as intermediate substrates, such as worse FPG, HbA1c and Alb1c, and/or as suboptimal insulin sensitivity and glucose load handling, among others." (PMID 40242065, 2025). "Furthermore, as evidence shows the advantages of is-CGM and rt-CGM in type 2 diabetes, the CloudCare concept is likely to also be applicable to people with type 2 diabetes, regardless of insulin use and despite the even greater challenges to use data of this group appropriately." (PMID 40165180, 2025). "The absence of insulin peaks may prevent the onset of type 2 diabetes." (PMID 39549141, 2025). "Metformin, a biguanide class antihyperglycemic agent widely prescribed for type 2 diabetes mellitus (T2DM), exerts its primary effect by activating AMP-activated protein kinase (AMPK) pathways, leading to reduced hepatic glucose production and enhanced insulin sensitivity." (PMID 40572709, 2025). "The management of blood glucose in a pregnant woman with type 1 diabetes is challenging, and the option of a glucose sensor or an insulin pump, both technologies recommended by current guidelines, may not be available for patients with either gestational or type 2 diabetes." (PMID 41020242, 2025). "Metabolic diseases—including type 2 diabetes, dyslipidemia, non-alcoholic fatty liver disease (NAFLD), and obesity—are increasing globally and share a central pathogenic mechanism: the accumulation of excess fat in non-adipose tissues, resulting in insulin resistance and organ dysfunction." (PMID 40869061, 2025). "However, in glucose-tolerant individuals with obesity, the ability of insulin to suppress plasma BCAA levels is diminished compared with that of lean individuals, and this impaired response is even more pronounced in individuals with type 2 diabetes compared with individuals with obesity." (PMID 40404819, 2025). "For example, higher serum cortisol levels are associated with decreased insulin secretion in the Japanese population, and higher morning cortisol levels are associated with increased FBG levels and reduced β-cell function in participants without type 2 diabetes." (PMID 40296149, 2025). "For adults with type 2 diabetes who are not taking insulin and who have limited health literacy or numeracy, or who are older and prone to hypoglycaemia, a simple and effective approach to glycaemia and weight management emphasizing appropriate portion sizes and healthy eating may be considered." (PMID 38778593, 2025). "Importantly, such receptor and IRS abnormalities have been observed in AD patients without type 2 diabetes, reinforcing the concept that central insulin resistance may arise independently and precede systemic metabolic dysfunction." (PMID 41294899, 2025). "However, despite these beneficial effects of exercise training, we showed that neither 10 weeks of endurance training nor 8 weeks of HIIT potentiated the insulin-induced suppression of plasma BCAAs in glucose-tolerant lean individuals, individuals with obesity or individuals with type 2 diabetes." (PMID 40404819, 2025).
type 2 diabetes (continued). "In 1957, Jean Stern converted the blood glucose-lowering potential of metformin in therapy for T2DM: he observed that, in subjects with maturity-onset diabetes, metformin could replace or reduce the need for insulin without the occurrence of frank hypoglycemia." (PMID 38668314, 2024). "In eight randomized controlled trials involving 7491 patients with type 2 diabetes mellitus (T2D), compared with GLP-1 RAs, insulin, and the placebo groups, body weight and blood pressure were reduced in the tirzetapide-treated groups of overweight/obese T2DM patients, which was dose-dependent." (PMID 38673991, 2024). "Therefore, the primary aim of this systematic review and meta-analysis was to give an up-to-date comprehensive overview of the effect of CGM (rtCGM or isCGM) compared with SMBG on glycaemic control, as quantified by HbA1c, in adults with type 2 diabetes treated with or without insulin." (PMID 38363342, 2024). "Finally, we could not differentiate between type I and type II diabetes and had no data on insulin levels." (PMID 39083723, 2024). "In type II diabetes mellitus, the pancreas may not secrete sufficient insulin, or the insulin produced may not be utilized effectively by the liver, muscles, and fat cells, leading to a condition known as resistance to insulin." (PMID 39771551, 2024). "When insulin release is no longer able to compensate for IR, it leads to disorders of carbohydrate metabolism, such as type 2 diabetes mellitus (T2DM)." (PMID 38398863, 2024). "Independent of obesity and family history of type 2 diabetes, a strong negative relationship exists between central abdominal fat (intra-abdominal plus abdominal subcutaneous fat) and whole-body insulin sensitivity, suggesting that central abdominal fat may be a strong marker of insulin resistance." (PMID 39769002, 2024). "Sensitivity analyses showed that insulin pump therapy was most cost-effective in individuals with the highest baseline HbA1c, suggesting that CSII may represent a cost-effective therapeutic alternative for MDI-treated type 2 diabetes populations who have HbA1c levels above target." (PMID 38951212, 2024). "It does not capture whether insulin-treated individuals have type 1 or type 2 diabetes." (PMID 39358593, 2024). "Fully closed-loop insulin delivery improved glucose control without increasing hypoglycemia compared with standard insulin therapy and may represent a safe and efficacious method to improve outcomes in adults with type 2 diabetes." (PMID 36631592, 2023). "Moreover, tagatose does not increase insulin in patients with Type-2 diabetes." (PMID 37475020, 2023). "Type 2 diabetes (T2D) is a non-autoimmune disease of impaired insulin signaling that afflicts ~10% of the population in the United State alone." (PMID 37460527, 2023). "Additionally, SUMOylation (SUMO) was identified as a regulator of PPARγ activity in our PPI analysis, offering a potential strategy for developing safer drugs for treating type 2 diabetes by inhibiting insulin-sensitizing activity without affecting adiposity in mice." (PMID 37445596, 2023). "However, that study was limited to analysis of type 2 diabetes as a binary disease trait, and did not investigate potential intermediate mechanisms such as those involving insulin secretion and sensitivity, and their genetic analysis was limited to lower-powered categorical BMI phenotypes." (PMID 36798216, 2023). "However, there are few trials in patients with type 2 diabetes and not on insulin." (PMID 37885536, 2023). "However, the study was limited to analysis of type 2 diabetes as a binary disease trait, and did not investigate potential intermediate mechanisms such as those involving insulin secretion and sensitivity; in addition, the genetic analysis was limited to lower-powered categorical BMI phenotypes." (PMID 37280435, 2023).
type 2 diabetes (continued). "Because patients who have insulin-dependent or Type I diabetes are vulnerable to hypoglycemia, which could lead to diabetic coma or death if their blood glucose level is not properly controlled using insulin or other drugs, blood glucose levels must be monitored often." (PMID 36832014, 2023). "Furthermore, fewer injections might facilitate treatment initiation in patients with type 2 diabetes who have not previously taken insulin, by reducing clinical inertia and promoting better acceptance of insulin therapy." (PMID 37249450, 2023). "Owing to the increasing prevalence of type 2 diabetes, the development of novel hypoglycemic drugs has become a research hotspot, with the ultimate goal of developing therapeutic drugs that stimulate glucose-induced insulin secretion without inducing hypoglycemia." (PMID 36204104, 2022). "It has not been elucidated whether incretins affect insulin clearance in type 2 diabetes (T2D)." (PMID 35169165, 2022). "Hence, an increase in the percentage of persons treated with “Insulin and non-insulin GLD” might reflect an increase in persons with type 2 diabetes not reaching treatment goals (in general, HbA1c > 53.0 mmol/mol (7%)) with non-insulin GLD only." (PMID 35701772, 2022). "The key clinical features of LADA and the requirement for no insulin at diagnosis mean that LADA shares similarities with type 2 diabetes (T2D)." (PMID 36090989, 2022). "Type 2 diabetes refers to a condition in which glucose is not used in fat, muscles, and liver tissues due to insulin resistance, and blood glucose concentration remains high, thereby leading to an increase in insulin secretion to maintain normal plasma glucose levels." (PMID 35956334, 2022). "In addition, the potentiation of insulin secretion by the two incretin hormones was found to be reduced in type 2 diabetes compared to nondiabetic individuals, but the entity of the reduction was somehow different between the two hormones (higher reduction with GIP)." (PMID 35625797, 2022). "Type 2 diabetes (T2D) (formerly adult-onset diabetes), a typically chronic illness, is characterized by high blood sugar, insulin resistance, and relative lack of insulin." (PMID 35954764, 2022). "People with obesity and type 2 diabetes (T2D) have lower postprandial insulin than those without T2D, and the relative insulin insufficiency is responsible for the marked hyperglycemia in people with T2D." (PMID 35054781, 2022). "In theory, hyperglycemia could be responsible for either nutrient renal losses or reduced immune defenses especially in the respiratory tract, even though hyperglycemia is generally not accompanied by reduced linear growth in the absence of insulin secretory defects (as in type 2 diabetes)." (PMID 35358060, 2022). "As a protease that avidly degrades insulin in vitro, IDE had been expected to mediate insulin clearance in vivo; however, emerging evidence has identified several non-proteolytic functions that might be perturbed in type 2 diabetes, implying a complex functional role for IDE." (PMID 35652923, 2022). "However, we found diminished basal serine-632 IRS-1 phosphorylation in obese muscle, and insulin only mildly activated serine phosphorylation, compared to unstimulated obese, as opposed to previous studies showing the hyperphosphorylation of serine-632 IRS-1 in the muscle cells of type 2 diabetes." (PMID 36547071, 2022). "Analyses of the brain tissue of AD and PD patients show insulin desensitization, independent of a previous history of type 2 diabetes mellitus (T2DM)." (PMID 35164216, 2022). "Furthermore, it was observed that monitoring for worsening glycemia due to burnout might be the best approach to using RT-CGM in people with type 2 diabetes who do not take prandial insulin." (PMID 37274843, 2022). "Type 2 diabetes mellitus (T2DM) is a non-infectious metabolic disease characterised by severe and persistent hyperglycaemia owing to decreased insulin secretion and increased insulin resistance." (PMID 36235257, 2022).